IL2 (interleukin 2)
Diseases named in the same sentence as IL2 in open-access papers (continued):
Sharing a sentence is not in itself a finding about the gene and the disease.
breast tumor (19 papers, 1997 to 2026). "Upregulation of genes encoding IL-2 and IL-7 has been associated with some classes of breast tumors; these were also upregulated in mammary glands of 10-week HFD-fed mice." (PMID 24156623, 2013). "Since the presence of IL-2 during blocking mAb treatment caused unwanted γδTc death, we investigated whether IL-2 is necessary for assessment of γδTc cytotoxicity against breast tumor targets." (PMID 28713391, 2017). "The cytokines TNF‐α and IL‐2, secreted by infiltrating immune cells at the tumor site in the breast tumor‐bearing model mice, were also significantly upregulated." (PMID 41476656, 2025). "CD4+, CD8+ and IL-2+ (p<0.05 for all) cells infiltration was also significantly increased in the breast tumor microenvironment of F3-treated mice compared with the tumors of untreated mice." (PMID 35972917, 2022). "For poorly differentiated breast tumors, an increase in the content of IL-1β, IL-2, IL-6, and IL-10 was observed, while the content of the rest decreased compared to the control group, but to a lesser extent than for highly differentiated tumors." (PMID 36286034, 2022). "In agreement with our findings in mice, a significant positive correlation between IL-31Ra and IL-2 mRNA levels was found in human breast tumors." (PMID 32843492, 2020). "γδTc TIL were extracted from a digested human breast tumor, expanded in vitro for 1 week in 1000 IU/ml IL-2, after which bulk TILs were maintained at 50 IU/ml IL-2." (PMID 25477885, 2014). "The Northern blotting results also suggested that the endogenous GrB mRNA detected in breast tumour cells was slightly larger than the GrB mRNA from IL-2-stimulated peripheral blood lymphocytes (PBL)." (PMID 12838314, 2003). "Several studies have provided evidence that enhanced tumor growth inhibition of breast tumors can be achieved by combining Doxorubicin with other agents such as zoledronic acid, interleukin-2, TGFβ Inhibitor, tetrathiomolybdate as opposed to treating with single agent." (PMID 21423660, 2011). "Reduced levels of activation-associated cytokines (IL-2, TNF-α, IFN-γ) are an important characteristic of exhausted T cells, and we report that the levels of these cytokines in CD8+ T cells isolated from spleens of mice-bearing mouse 4T1 breast tumours are, as expected, similarly reduced." (PMID 31594465, 2019). "An anti‐CEA ICK (M5A‐IL‐2) was compared to an IL‐2‐Fc fusion protein using tumor therapy and PET imaging in CEA transgenic immunocompetent mice bearing CEA positive colon or breast tumors." (PMID 38317590, 2024). "IL‐2‐Fc and ICK were conjugated with NHS‐DOTA, radiolabeled with 64Cu, and injected into female CEA transgenic mice (CEAtg) bearing orthotopic E0771/CEA breast tumors." (PMID 38317590, 2024). "Meanwhile, zinc nanoparticles loaded with porphyrin-lipid photosensitizer used for PDT in 4T1 breast tumors also reported an increase in serum TNF-α, IFNγ, and IL-2, one day after PDT." (PMID 36405502, 2021). "Taking all of our previous results into account, we designed parallel blocking-only and blocking plus cytotoxicity assays, in the absence of IL-2, to assess the involvement of γδTCR in killing T47D breast tumor targets, while considering anti-γδTCR mAb-induced effector cell death." (PMID 28713391, 2017). "In addition, it was found that IL-2 significantly decreased the expression of the inhibitory receptor CTLA-4 and increased the expression of B lymphocyte-induced maturation protein-1(Blimp-1), leading to the activation of effector T cells and the induction apoptosis of the breast tumor cells." (PMID 42192107, 2026).
hepatitis B (19 papers, 2012 to 2025). "For HC, IL2 release after HBsAg stimulation depicted hepatitis B vaccination status with a diagnostic sensitivity and specificity of 85 % and 90 %." (PMID 25968473, 2015). "Levamisole, IL-2, and granulocyte-macrophage colony-stimulating factor (GM-SF) are commonly employed as vaccine adjuvants in recombinant hepatitis B vaccines." (PMID 39057781, 2024). "The immune simulation results of the classical hepatitis B vaccine closely aligned with the responses observed in real vaccine immunizations, such as significant increases in IL-2- and TNF-α-producing cells, particularly CD8+ T cells." (PMID 39703502, 2024). "IL-2 and IFNγ release in this assay depicts hepatitis B vaccination status." (PMID 30602374, 2019). "However, the direct use of whole blood ex vivo and the cytokine IL2 as a novel T cell readout marker might be an attractive alternative in case of future hepatitis B vaccination studies." (PMID 25968473, 2015). "Since HBsAg is a main component of the prophylactic hepatitis B vaccine it does not surprise that the HBsAg-mediated production of the cytokines IL-2 and IFNγ correlates with the blood donors’ vaccination status as published previously." (PMID 30602374, 2019). "Seventy two chronic Hepatitis B patients (CHB), 8 acute hepatitis B patients (AHB) and 80 healthy controls (HC) were tested by ELISA for IFNγ- and IL2-secretion in whole blood after challenge with synthetic peptide libraries of hepatitis B core antigen (HBcAg) or hepatitis B surface antigen (HBsAg)." (PMID 25968473, 2015). "In this paper, we demonstrate in a mouse model that a chronic Schistosoma japonicum infection can inhibit the immune response to hepatitis B vaccine (HBV vaccine) and lead to lower production of anti-HBs antibodies, interferon-γ (IFN-γ) and interleukin-2 (IL-2)." (PMID 23272112, 2012).
Pruritus (19 papers, 2014 to 2025). Pruritus is an itch or a sensation that makes a person want to scratch. "Based on these discussions, the increased ZAP70 cause IL-2 increased and severe pruritus." (PMID 27195291, 2016). "In psoriasis, pruritus involves Substance P, IL-2, calcitonin gene-related peptide (CGRP), μ-opioid receptors (OPRM), and κ-opioid receptors (OPRK), while in AD pruritus is linked to thymic stromal lymphopoietin (TSLP), CGRP, IL-4, IL-13, and IL-31." (PMID 39859462, 2025). "Therapeutics specifically targeting IL-2 or its receptor have not been developed for chronic itch relief; however, gabapentin has been proposed as a treatment option in IL-2-related pruritus, but this requires final investigation at the clinic level." (PMID 36077340, 2022). "IL-2 is an itch inducer as well as an autocrine cytokine, and its single intradermal injection induces a long-time low-intensity local skin itch that lasts 48–72 h, as well as erythema in human AD patients and healthy subjects." (PMID 36077340, 2022). "A study carried out on 30 patients suffering from pruritus showed increased IL-2 levels compared to healthy individuals." (PMID 32664385, 2020). "Altogether, more research is required to decipher the precise role of IL-2 in pruritus or mediation of itch sensation." (PMID 32664385, 2020). "The biomarkers of uremic pruritus (serum hs-CRP and IL-2) and severity of pruritus (scale by VAS and PS) are lower in vegetarian diet patients and vegetarian diet conversion." (PMID 30396306, 2018). "IL-2 is a pruritic cytokine secreted by T helper 1 (Th1) cells and systemic IL-2 injection can result in pruritus." (PMID 30396306, 2018). "STAT1, IL2, and NF-κB are in the toll-like receptor signaling pathway and are related to pruritus pathogenesis." (PMID 28869563, 2017). "In conclusion, our study demonstrates that increased ZAP70 participates in the development of dry skin in elder pruritus via secretion of IL-2 and NGF." (PMID 27195291, 2016). "Several cytokines including IL-2, Il-8 and IL-31 have been related to itch induction and it has been shown that IL-2 levels increase at night." (PMID 27011178, 2016). "IL-2 is normally produced by T cells during an immune response and has a well-documented role in the induction of pruritus in AD." (PMID 26221169, 2015). "Although antihistamines are used for IL-2 induced pruritus, one study has reported, and anecdotal reports have suggested, that gabapentin has a major beneficial effect on pruritus." (PMID 31546315, 2014). "However, IL-10 expression was shown to be increased in CSU lesions and a CSU mouse model overexpressing IL-10 exhibited increased pruritus and increased IL-2, IL-4, and IFN-γ expression, driven by JAK/STAT signaling." (PMID 35872776, 2022). "This hypothesis was supported by the elevated serum levels of the C-reactive protein (CRP) and the inflammatory cytokines interleukin (IL)-2 and IL-6 in HD patients with pruritus versus those free from pruritus." (PMID 35324695, 2022). "Patient's baseline information before therapy and clinical symptoms after therapy were observed and compared, including pruritus ani score, anus drainage and damp score, skin lesion score, skin lesion area score, life quality index score, and IL-2, IL-4, and IgE levels in serum." (PMID 34721653, 2021). "The authors hypothesized that increased β2-M concentration might stimulate production or accumulation of IL-2 or TNF-α, with subsequent activation of CD4 lymphocytes, thereby increasing the risk of pruritus." (PMID 34209560, 2021). "The pruritus score improved and IL-2 level decreased after change to vegetarian diet." (PMID 30396306, 2018). "Another study showed that increased ZAP70 is involved in dry skin in elderly pruritus, while increased secretion of IL-2 and NGF may induce dry-skin itching." (PMID 30018382, 2018). "Uncommonly, skin excoriation as a result of pruritus may delay the second cycle of IL-2, if there are open lesions and severe redness." (PMID 31546315, 2014).
Pruritus (continued). "Rarely pruritus or cutaneous toxicity can accelerate, particularly during the second cycle of IL-2 treatment, and the sensation may become intolerable, despite treatment." (PMID 31546315, 2014). "Pruritogens, including TAC1, IL-2, IL-31, TPSAB1, TPSB2, and TPSG1, and the key enzymes that are attributed to itch, including HDC and TPH1, were detected by RNA-seq." (PMID 35632808, 2022). "The inhibition of JAK ensures the inhibition of receptors; therefore, the subsequent biological effects, from a greater number of cytokines, are variably involved in the pathogenesis of pruritus, not only IL13 and IL4 but also IL31, IL2, IL8, IL25, IL33, IFNγ and thymic stromal lymphoprotein (TSLP)." (PMID 35890180, 2022). "A small study has shown that pruritus is not related to the eosinophilia that sometimes develops with HD IL-2 administration." (PMID 31546315, 2014). "Notably, IL-2 has been utilized therapeutically (e.g., in metastatic renal carcinoma or melanoma), with pruritus not infrequently occurring as an adverse event." (PMID 34209560, 2021). "First, patients undergoing hemodialysis who develop pruritus with no obvious visible signs of inflammation have significantly higher serum levels of C-reactive protein, IL-6, IFN-γ, IL-2, and IL-31 than patients without pruritus." (PMID 40596915, 2025).
ZIKV infection (19 papers, 2017 to 2026). "For example, Zika virus infection was associated with an increased secretion of IL2, IL4, IL13, and IL9 cytokines." (PMID 29937515, 2018). "Thus, the loss of detectable IL-2 after ZIKV infection in CD14-depleted PBMCs would further reduce NK cell priming." (PMID 29600283, 2018). "The detection of cytokines such as IL-2, IL-4, and IL-17 in individuals in the acute phase of ZIKV infection suggests a polyfunctional response profile characterized by Th1, Th2, and Th17 responses." (PMID 37514084, 2023). "Cytokine profiles in acute ZIKV infections were estimated using a multiplex bead analysis assay which measured interleukin (IL) 1β, IL-2, IL-4, IL-6, IL-8, IL-9, IL-10, IL-13, and IL-17." (PMID 30682026, 2019). "Overall CD4 T cell responses to the ZIKV structural proteins were determined by IL-2 ELISPOT assays using PBMCs from 14 patients with laboratory-confirmed ZIKV infection and peptide pools of C, prM, and E." (PMID 29899743, 2018). "In addition to these cytokines, GM-CSF, IL-1B, IL-2, IL-6, IL-17, and IL-22 have been observed in the acute phase of Zika virus infection." (PMID 41417343, 2025). "Alternatively, FcRγ expression is associated with NK cell proliferation in response to cytokines, which could be driven by IL-2, IL-12, and IL-18, all of which are upregulated in acute ZIKV infection." (PMID 41000887, 2025). "Adult ZIKV infection is associated with immune activation with upregulation of cellular markers, including CD69, Ki67 and increases insoluble markers, including MCP-1, IL-2, IL-15, vascular endothelial growth factor (VEGF) and IL-10 in the first few days post-infection." (PMID 35130924, 2022). "IL-2 levels were comparable among the arbovirus groups (though higher in DENV and patients with ZIKV infection than in controls)." (PMID 41547724, 2026). "Given the importance of T cell responses in controlling ZIKV infection, we measured the ability of ZIKV specific T cell populations from immunized mice to secrete IFN‐γ, TNF‐α, and IL‐2 in response to ZIKV E protein stimulation." (PMID 39010673, 2024). "The results suggest that ZIKV infection cells hinder JEG3 cell cycle control, the ERAD pathway, and IL-7 interactions and promote mRNA decay and processing (as well as alternative splicing) and the IL-2 pathway." (PMID 36015056, 2022). "Upon polyclonal stimulation ZIKV infection triggered an expansion of CD8+ T cells expressing IL-2, CD107a, Granzyme B and Perforin, but not IFNγ." (PMID 30087337, 2018). "In addition, KLRG1+ CD8+ effector T cells and effector memory T cells as well as CD8+ T cells expressing granzyme B, interleukin 2 (IL-2) and IFN-γ were more frequently detected in B6 mice following ZIKV infection, indicating the activation of CD8+ T cell response in vivo." (PMID 40920828, 2025). "ZIKV infection induced in nonpregnant women significantly higher levels of the anti-inflammatory cytokine IL-10, and increased pro-inflammatory cytokines IL-6, IL-2, IFN-α, and IFN-γ, and decreased levels of IL-1β in relation with uninfected, nonpregnant women." (PMID 33430059, 2021). "ZIKV infection triggered the upregulation of multiple cytokines in humans during acute phase of infection that we were able to characterize by Luminex assay, including IP-10, IL-5, GM-CSF, TNF-α, IL-15, IL-10, MIP-1α, IFN-γ, IL-6, IL-1RA, IL-2, MIG, IFN-α, IL-2R, and IL-4." (PMID 30333476, 2018). "The Th1 cells induced by ZIKV infection also exhibited a high degree of poly-functionality (multiple cytokine production), as over 65% of responding CD11a+CD49d+ CD4+ T cells were IFN-γ+TNF-α+ double-producers, and over 60% were IFN-γ+TNF-α+IL-2+ triple-producers." (PMID 28231312, 2017).
delirium (18 papers, 2012 to 2025). A disorder characterized by confusion; inattentiveness; disorientation; illusions; hallucinations; agitation; and in some instances autonomic nervous system overactivity. "Again, delirium was associated mostly with higher expression, but the inverse was true preoperatively for myoglobin (MB), IL-2, and IL-20, and postoperatively for chemokine ligand 15 (CCL15) and TNF-related apoptosis-inducing ligand (TRAIL)." (PMID 37156856, 2023). "High levels of IL-2 were associated with a higher risk of delirium following cardiac surgery in another study." (PMID 27119013, 2016). "The final multivariateregression analysis revealed that the preoperative cortisol level, MDD, impairedexecutive functions, higher creatinine and IL-2 concentrations and a higher dosage ofmidazolam independently increase the risk of postoperative delirium." (PMID 23452669, 2013). "This study evaluated the effect of nine genetically predicted inflammatory factors (TNF-α, CPR, IL-1α, IL-1β, IL-2, IL-6, sIL-6Rα, Soluble gp130, and IL-8) on delirium." (PMID 37649721, 2023). "Our previous prospective study conducted among cardiac surgery patients revealed that raised levels of IL-2 and TNF-α measured in the postoperative period are associated with the development of delirium among CABG surgery patients." (PMID 33918634, 2021). "Immunotherapy with cytokines can induce delirium (IL-2, IFN) and increased systemic cytokines and acute phase proteins (IL-6, IL-8, CRP) are associated with delirium post hip fracture." (PMID 20471138, 2012). "Furthermore, several studies have examined the potential role of IL-1α, IL-1β, IL-2, and IL-8 in the development of delirium." (PMID 37649721, 2023). "The results of this MR analysis did not support that peripheral TNF-α, CRP, IL-1α, IL-1β, IL-2, IL-6, sIL-6Rα, soluble gp130, and IL-8 were causally associated with delirium." (PMID 37649721, 2023). "Patients with MDD who were administered T-cell cytokines including IL-2 exhibited remarkable alterations in depressive-like behavior, including depressed mood, fatigue, cognitive dysfunction, and sleep impairment, as well as in psychosis and delirium." (PMID 31215856, 2020). "We assessed the relationships between levels of preoperative thyroid hormone (TH), cortisol, interleukin-2 (IL-2), and procalcitonin (PCT) and postoperative delirium (POD) in acute type A aortic dissection (ATAAD) patients receiving modified triple-branched stent-graft (MTBSG) implant surgeries." (PMID 36434500, 2022). "We previously used mass-spectrometry-based plasma proteomics to define a preoperative delirium multi-protein signature that includes zinc-alpha-2-glycoprotein (AZGP1) and c-reactive protein (CRP) and a postoperative signature of interleukin-6 (IL-6), interleukin-2 (IL-2), and CRP." (PMID 39199312, 2024). "In summary, the MR analysis indicated that there may not be a causal association between delirium and the following factors: TNF-α, CRP, IL-1α, IL-1β, IL-2, IL-6, sIL-6Rα, soluble gp130, and IL-8." (PMID 37649721, 2023). "Inflammatory markers such as IL-6, IL-2, TNF-α, and C-reactive protein have been found to be elevated in POD patients compared to those without delirium." (PMID 40092071, 2025).
dementia (18 papers, 2018 to 2025). Loss of intellectual abilities interfering with an individual's social and occupational functions. "Consistently, elevated peripheral pro-inflammatory cytokines (IL-1β, TNF-α, IL-2) have been reported in dementia patients." (PMID 41291751, 2025). "Patients with moderate to severe AD have been previously shown to have elevated serum IL-2 levels which correlated with dementia severity." (PMID 39526037, 2024). "There is a growing body of evidence that both local and systemic inflammation are important in dementia, our present data also demonstrated that Gao-Zi-Yao exerts regulation effects on systemic inflammation by decrease of IL-1β, IL-2 and." (PMID 35643519, 2022). "However, IL‐2, a potent activator of T‐cell differentiation and proliferation, showed a significant main effect for dementia status (dementia, F = 4.728, p = 0.0390), whereby AD individuals had higher IL‐2 content compared to controls." (PMID 41031399, 2025). "In previous studies, elevated peripheral vascular cell adhesion molecule-1, tumor necrosis factor (TNF)-α, IL-2, IL-6, IL-18, and interferon-γ were found in patients with mild AD, suggesting that cytokine signaling might play a role in the intermediate stages of dementia." (PMID 35069588, 2021). "Specifically, we found significantly higher levels of IL-10, IL-1beta, IL-4 and IL-2 in both MCI-LB and MCI-AD compared with dementia and control subjects." (PMID 29248892, 2018).